MALAT1 (metastasis associated lung adenocarcinoma transcript 1)
Diseases named in the same sentence as MALAT1 in open-access papers (continued):
Sharing a sentence is not in itself a finding about the gene and the disease.
osteosarcoma (continued). "In human osteosarcoma cell lines, the knockdown of MALAT1 by siRNA affected the PI3K/AT signaling pathway and inhibited invasion and metastasis in vitro and in vivo." (PMID 28353666, 2017). "As miR-205 has been reported to be involved in osteosarcoma progression, we focus on the interaction between MALAT1 and miR-205." (PMID 29290978, 2017). "Spearman correlation assay showed that MALAT1 negatively correlated with miR-205 expression in osteosarcoma tissues." (PMID 29290978, 2017). "Lastly, through the vivo experiment of nude mice, we also found that the transfection of MALAT1 shRNAs slowing down the rate of tumor formation in vivo, inhibited lung metastasis of osteosarcoma cells." (PMID 28938647, 2017). "Kaplan–Meier survival analysis and multivariate Cox regression analysis revealed MALAT1 expression to be an independent prognostic factor for the shorter overall survival rate observed in osteosarcoma patients." (PMID 28353666, 2017). "Our Kaplan–Meier analysis and log-rank test revealed that a high expression of MALAT1 was inversely correlated with osteosarcoma patients’ overall survival." (PMID 28938647, 2017). "While the expression of MALAT1 was higher in osteosarcoma tissues and cell lines, miR-205 expression was significantly lower (P<0.01)." (PMID 29290978, 2017). "Knockdown of MALAT1 inhibited the proliferation of human osteosarcoma cell lines via the phosphatidylinositol 3-kinase (PI3K)/Akt signaling pathway." (PMID 28353666, 2017). "The aim of this study is to investigate the clinical experimental function of MALAT1 in human osteosarcoma and further investigate the potential regulatory mechanism by which MALAT1 participate in osteosarcoma progression." (PMID 29290978, 2017). "Here, we clarified that MALAT1 was highly expressed in osteosarcoma and that down-regulation of MALAT1 decreased migration/invasion and proliferation in osteosarcoma cells MNNG/HOS." (PMID 28938647, 2017). "Firstly, we detected the expression of MALAT1 in 20 osteosarcoma tissues and paired para-tumor bone tissues by using real-time quantitative PCR (qRT-PCR)." (PMID 28938647, 2017). "Subsequently, The gain and loss functional assay indicated that miR-205 was significantly increased after knockdown of MALAT1 in osteosarcoma cells, while enhanced expression of miR-205 dramatically silenced MALAT1 expression level in osteosarcoma cells." (PMID 29290978, 2017). "RT-qPCR analysis showed that MALAT1 expression was significantly increased in primary osteosarcoma tissues and cell lines." (PMID 29290978, 2017). "In the present study, an elevated MALAT1 was found in osteosarcoma tissues and cell lines, and the elevated MALAT1 was correlated with a poor prognosis in osteosarcoma patients." (PMID 28938647, 2017). "In conclusion, we revealed that enhanced MALAT1 expression predicted unfavourable outcome in osteosarcoma and promoted cell proliferation through suppressing miR-205 and activating SMAD4 function." (PMID 29290978, 2017). "Subsequently, the MALAT1 expression in four osteosarcoma cell lines (MG-63, SAOS-2, U2OS, SW1353) and one osteoblastic cell line (hFOB) were also determined." (PMID 29290978, 2017). "Cai X found that MALAT1 was up-regulated and functioned as an oncogene in osteosarcoma via RhoA and its downstream ROCKs." (PMID 28938647, 2017). "All these findings confirmed that up-regulation of MALAT1 promoted pulmonary metastasis of osteosarcoma via the miR-144-3p/ROCK1/ROCK2 pathway in vivo." (PMID 28938647, 2017). "In this study, we sought to determine the clinical and bilogical role of MALAT1 in osteosarcoma progression." (PMID 29290978, 2017). "In brief, all the data above confirmed that MALAT1 promoted proliferation/metastasis by promoting ROCK1/ROCK2 via a ceRNA of miR-144-3p in osteosarcoma cells MNNG/HOS." (PMID 28938647, 2017).
osteosarcoma (continued). "In order to understand the role of MALAT1 in cellular proliferation, we synchronized human osteosarcoma cells (U2OS) in specific cell cycle stages and examined the levels of MALAT1 in each stage of the cell cycle." (PMID 23555285, 2013). "Similarly, in osteosarcoma, MALAT1 is overexpressed and serves as a predictor of unfavourable patient survival." (PMID 39323624, 2024). "Additionally, MALAT1 demonstrated oncogenic functions, increasing osteosarcoma cell growth potentially through the stimulation of the PI3K/AKT and RhoA/ROCK pathway." (PMID 39015175, 2024). "In particular, Bone Marrow Mesenchymal Stem Cells-Derived Extracellular Vesicles (BMSC-EVs) were found able to promote proliferation, invasion and migration of osteosarcoma cells via the MALAT1/miR-143/NRSN2/Wnt/beta-catenin axis both in vitro and in vivo, as detailed in a next section." (PMID 38835012, 2024). "The transcription factor FOXO1 modulated MALAT-1 in osteosarcoma." (PMID 38201661, 2024). "The degradation of MALAT1 mediated by miR-9 was shown in osteosarcoma cells MG-63 that were treated with 17β-estradiol, which increased miR-9 levels, degraded MALAT1, and reduced several cancer hallmarks, including cell proliferation, colony formation, migration, and invasion (right)." (PMID 38473229, 2024). "The replication and migration of osteosarcoma cells was inhibited following MALAT1 knockdown." (PMID 39015175, 2024). "E-cadherin expression rises and osteosarcoma cell invasion is reduced when MALAT1 is suppressed." (PMID 39323624, 2024). "For example, lncRNA MALAT1 was a valuable biomarker for the prognosis of osteosarcoma." (PMID 38194709, 2024). "Furthermore, MALAT1 levels correlated with high miR-34a expression in the tested osteosarcoma cells, which was previously also reported for melanoma cells." (PMID 37048099, 2023). "This study showed that MALAT1, via the downregulation of miR-376a, accelerates osteosarcoma via the Wnt/β-catenin pathway, which is a conserved signaling axis participating in diverse physiological processes such as proliferation, differentiation, apoptosis, migration, and invasion." (PMID 36012617, 2022). "LncRNA MALAT1 has been discovered to regulate stem cell expression in osteosarcoma." (PMID 35252166, 2022). "The lung metastasis of primary osteosarcoma is an understudied topic with regards to a possible role of lncRNAs, and the only available report is the one that described a possible involvement of lncRNA MALAT1." (PMID 34386496, 2021). "Furthermore, three studies reported the diagnostic power of circulating HNF1A-AS1 (Cai 2017), FAL1 (Wang 2017) and MALAT1 (Huo 2017) lncRNAs to be more effective than alkaline phosphatase (ALP) in distinguishing osteosarcoma from healthy individuals." (PMID 34439367, 2021). "For instance, MALAT1 regulates osteosarcoma progression and facilitates lung metastasis by targeting several miRNA families, promotes thyroid cancer progression by regulating miR-204, and leads to chemoresistance in hepatocellular carcinoma by sponging miR-140-5p." (PMID 34439367, 2021). "MALAT1 is upregulated in lung metastatic osteosarcomas and thus miR-202 is down-regulated." (PMID 32728178, 2020). "It is possible that MALAT1 might be involved in metastasis of osteosarcomas to other metastatic sites as well." (PMID 32728178, 2020). "Therefore, we were interested in finding a miRNA that was functionally involved in lncRNA MALAT1’s actions towards promoting lung metastasis of osteosarcoma." (PMID 32728178, 2020). "MALAT1 has also been shown to promote development of osteosarcoma by targeting TGFA via miR-376A." (PMID 32503170, 2020). "In conclusion, MALAT1-miR-202 represents a potential lncRNA-miRNA signature that affects lung metastasis of osteosarcomas and could potentially be targeted for therapy." (PMID 32728178, 2020).
osteosarcoma (continued). "Moreover, when MALAT1 is downregulated, it leads to much reduced lung metastases of otherwise metastatic osteosarcoma cells." (PMID 32728178, 2020). "In osteosarcoma, several studies have shown Malat1 can function as a ceRNA for different miRNAs." (PMID 31616462, 2019). "A number of studies have shown that MALAT1 has carcinogenic effect in osteosarcoma tumorigenesis and metastasis, so it can be considered that MALAT1 may be a promising therapeutic target for osteosarcoma patients." (PMID 30936265, 2019). "MALAT1 promotes the progression of osteosarcoma via upregulation of RhoA, ROCK and Rac1." (PMID 31248165, 2019). "Long noncoding RNA (LncRNA) metastasis-associated lung adenocarcinoma transcript 1 (MALAT1), an lncRNA with notorious roles in multiple aggressive tumors, was reported to promote osteosarcoma development by up-regulation of HMGB1 via hsa-miR-142-3p and hsa-miR-129-5p." (PMID 29899164, 2018). "Moreover, the knockdown of MALAT-1 reduces the formation of acting stress fibers and vasculogenic mimicry (VM) in three-dimensional cultures, referring to the ability of osteosarcoma cells to form alternative circulatory systems." (PMID 29657304, 2018). "Taken together, MALAT-1 may constitute a therapeutic target in the management of osteosarcoma, in order to inhibit cellular proliferation, migration, and invasion." (PMID 29657304, 2018). "In addition, recent studies revealed that the lncRNA MALAT1 was dysregulated in multiple malignant tumors, including osteosarcoma." (PMID 29441193, 2018). "Knockdown of MALAT1 decreased proliferation, migration, and induced apoptosis in osteosarcoma." (PMID 29441193, 2018). "This study confirmed silenced MALAT1 inhibited osteosarcoma growth both in vitro and in vivo." (PMID 29245999, 2017). "This study reported that MALAT1 was up-regulated two folds in osteosarcoma tissues and a knockdown of MALAT1 could suppress the tumor growth via PI3K/AKT signaling pathway." (PMID 29245999, 2017). "Secondly, we tried to assess whether the elevated MALAT1 was correlated with the final survival time of osteosarcoma by using qRT-PCR." (PMID 28938647, 2017). "The functional experiments show that a decreased MALAT1 could remarkably inhibit osteosarcoma cell metastasis and proliferation but induce cell cycle arrest, indicating that MALAT1 functioned as an oncogene in osteosarcoma." (PMID 28938647, 2017). "The results indicated that MALAT1 was upregulated while miR-205 was suppressed in osteosarcoma." (PMID 29290978, 2017). "The level of MALAT1 was closely correlated with pulmonary metastasis in human osteosarcoma tissue." (PMID 28353666, 2017). "Suppression of MALAT1 could be a future direction to promote the clinical outcome of osteosarcoma patients." (PMID 29290978, 2017). "Since elevated MALAT1 was closely related to distant metastasis in osteosarcoma patients, we tried to explore the potential function that MALAT1 may work on migration and invasion in the osteosarcoma cell line MNNG/HOS." (PMID 28938647, 2017). "The findings of the present study indicated that MALAT1 might be a new target in the molecular therapeutic of osteosarcoma." (PMID 28938647, 2017). "Collectively, these results suggest that MALAT1 is up-regulated and could be an independent prognostic factor in osteosarcoma." (PMID 29290978, 2017). "Also, we measured MALAT1 expression in osteosarcoma cell lines MG-63, U2OS, MNNG/HOS and a human osteoblast cell line hFOB 1.19 via the same method." (PMID 28938647, 2017). "In summary, the findings of this study based on the ceRNA theory, combining the research foundation of miR-144-3p, ROCK1 and ROCK2, taking MALAT1 as a new point of study, provided new insights into molecular level proliferation reversal and metastasis of osteosarcoma." (PMID 28938647, 2017). "Our results indicate that MALAT1 could be a potential therapeutic target in molecular targeting treatment of osteosarcoma." (PMID 28938647, 2017).
osteosarcoma (continued). "Finally, through the use of murine models, we confirmed that MALAT1 worked in a facilitative role on osteosarcoma tumorigenesis and metastasis." (PMID 28938647, 2017). "In conclusion, the present study demonstrated that MALAT1 was elevated in osteosarcoma." (PMID 28938647, 2017). "Also, as shown in the fore-mentioned section, there was a close relation between elevated MALAT1 and tumor size in osteosarcoma patients." (PMID 28938647, 2017). "They showed that MALAT1 knockdown inhibited osteosarcoma cell proliferation and migration, induced osteosarcoma cell cycle arrest and cell apoptosis, and delayed tumor growth in an osteosarcoma xenograft model." (PMID 27685633, 2016). "Moreover, they found that MALAT1 knockdown suppressed human osteosarcoma cell proliferation, invasion, and metastasis in vitro and in vivo." (PMID 27685633, 2016). "Notably, MALAT1 is highly expressed in two canine osteosarcoma cell lines, COS3600 and COS4074." (PMID 37999460, 2023). "MALAT1, which is a beneficial factor in the case of hypoproliferative disorders, may assume an adverse role in the context of oncogenesis, where overexpression of MALAT1 stimulates formation of new endothelial cells, hence, promoting angiogenesis in osteosarcoma." (PMID 37947637, 2023). "Long non-coding RNA Metastasis-associated lung adenocarcinoma transcript 1 (MALAT-1), one of the first lncRNAs identified, is overexpressed in osteosarcoma cell lines Saos-2, U2OS and HOS compared with the osteoblast cell line hFOB1.19 (p < 0.05), and is overexpressed in human osteosarcoma tissues." (PMID 29657304, 2018). "Thus, lncRNA MALAT1 may serve as a promising prognostic and therapeutic target for osteosarcoma patients." (PMID 29290978, 2017). "Finally, we sought to establish the regulatory pathway of MALAT1-miR-205-SMAD4 in osteosarcoma." (PMID 29290978, 2017). "Finally, we demonstrated that MALAT1 promoted osteosarcoma progression via a miR-205-SMAD4 axis." (PMID 29290978, 2017). "MALAT1, also known as NEAT2, is a highly conserved lncRNA overexpressed in several human cancers and linked to enhanced cell proliferation, migration, and/or invasion of cancers, such as: prostate, breast, lung, liver, esophageal, pancreatic, gastric, colorectal, bladder, cervical, and osteosarcoma." (PMID 27600237, 2015). "This study primarily demonstrated that reduced expression of MALAT1 leads to an increased binding affinity between SRSF1 and pre-mRNA (B-MYB and CENPE), thereby regulating alternative splicing mechanisms in osteosarcoma cells." (PMID 41019082, 2025). "Another investigation demonstrated that hsa-miR-425-5p inactivates the Wnt/β-catenin signaling pathway, consequently reducing the expression of MALAT1 and TUG1 in osteosarcoma, thereby inhibiting tumor progression." (PMID 38383747, 2024). "The in vivo and in vitro lentivirus-mediated siRNA reduction of MALAT1 expression decreases in PCNA, MMP-9, p-PI3K, and RhoA/ROCKs expression, which then attenuates the growth, invasion, and dissemination of osteosarcoma cells." (PMID 39015175, 2024). "Studies show that MALAT-1 regulates PI3K/Akt in several cancers, such as osteosarcoma, gastric, breast, and cervical." (PMID 38201661, 2024). "MALAT1 can also regulate TGF-expression by targeting miR-376a, which promotes osteosarcoma development." (PMID 37244966, 2023). "MALAT1 regulates the expression of the cell cycle protein-dependent kinase 9 (CDK9) by sponging miR-206, thereby controlling the progression of osteosarcoma." (PMID 36903369, 2023). "MALAT1 promoted proliferation and metastasis via sponging miR-144-3p and blocking ROCK1/ROCK2 axis in osteosarcoma cells." (PMID 35252166, 2022).
osteosarcoma (continued). "This study suggested that MALAT1 enhanced stem cell-like features via promotion of RET expression via targeting miR-129-5p and subsequently activating the PI3K-Akt pathway in osteosarcoma." (PMID 35252166, 2022). "MALAT1 can increase the expression of TGFA and promote the proliferation and metastasis of osteosarcoma by inhibiting mir376a." (PMID 35903358, 2022). "In consistent, depletion of MALAT1 reduced the expression of CD90, CD133 and SOX2 in osteosarcoma cells." (PMID 35252166, 2022). "The lncRNAs MALAT1 and HNF1A-AS1 promote cell proliferation and metastasis in osteosarcoma by activating the PI3K/Akt and Wntβ-catenin signaling pathways, respectively." (PMID 31850493, 2020). "A few other commonly studied osteosarcoma cells also had higher MALAT1 levels than hFOB 1.19 cells, such as, MG63, SAOS-2 and U2OS but the MALAT1 levels were clearly the highest in KRIB cells." (PMID 32728178, 2020). "Similar studies using Malat1-targeting siRNAs have been conducted in other cancer types, such as glioblastoma, ovarian, colorectal (CRC), gallbladder, gastric, osteosarcoma, and esophageal, etc.." (PMID 32503170, 2020). "Further, among the osteosarcoma cell lines that we tested, U2OS are poorly metastatic and thus lower MALAT1 levels in these cells also make sense." (PMID 32728178, 2020). "In osteosarcoma, MALAT1 can promote cancer metastasis, mediated by activation of the PI3K/Akt signaling pathway, and the FOXO1-MALAT1-miR-26a-5p feedback loop." (PMID 32708561, 2020). "With regard to osteosarcoma, lncRNAs such as HOTAIR, HULC, H19 and MALAT-1, have been identified to be aberrantly expressed in cancer and function with underlying mechanisms." (PMID 31443665, 2019). "MALAT-1 seems to exert its oncogenic function via regulating the Ras homolog gene family, member A (RhoA)/Rho-Kinase (ROCK)-pathway, as downregulation of MALAT-1 reduces protein levels of RhoA, ROCK1 and 2 in osteosarcoma cell lines U2OS and HOS." (PMID 29657304, 2018). "Inhibition of MALAT1 decreased metastasis and proliferation by regulation of ROCK1/ROCK2 via ceRNA of miR-144-3p in osteosarcoma cells in vitro." (PMID 28938647, 2017). "More importantly, we further uncovered that MALAT1 mediated cell proliferation and cell cycle arrest through a miR-205-SMAD4 signaling pathway in osteosarcoma cells." (PMID 29290978, 2017). "Collectively, we demonstrated that MALAT1 promotes cell proliferation through suppressing miR-205 and promoting SMAD4 expression in osteosarcoma." (PMID 29290978, 2017). "Nine different long non-coding RNAs were studied in these 10 included articles, with 7 lncRNAs including MALAT1, BCAR4, FGFR3-AS1, HOTAIR, TUG1, FOXC2-AS1 and PVT1 were up-regulated in osteosarcoma cells or patients." (PMID 29245999, 2017). "Thus, lncRNA MALAT1 may be a potential prognostic and therapeutic target in osteosarcoma." (PMID 29290978, 2017). "In addition, lncRNA MALAT1 sponged miR-150-5p and increased the expression of VEGFA and enhanced tumor angiogenesis in osteosarcoma." (PMID 35992869, 2022). "BMSC-EVs can transfer MALAT1 into osteosarcoma cells, thus increasing the expression of MALAT1 and NRSN2, reducing the expression of miR-143, and activating Wnt/β-catenin pathway in osteosarcoma cells." (PMID 35860555, 2022). "miR-202 was reported to be a direct downstream target of MALAT1 in different types of tumors including NSCLC, osteosarcomas, gastric, and cervix carcinoma, where a negative correlation was found between the expressions of MALAT1 and miR-202." (PMID 35682549, 2022). "MALAT1 and DLEU2 have been shown to promote osteosarcoma progression in previous studies." (PMID 34456631, 2021). "Furthermore, MALAT1/miR-144-3p/ ROCK1 axis promoted the proliferation and metastasis of osteosarcoma." (PMID 33639865, 2021). "So, we analyzed the remaining seven studies after eliminating this one, and the predicted tendence of MALAT1 in osteosarcoma was not altered (HR = 2.20, 95%CI: 1.70–2.85, P < 0.001)." (PMID 33639865, 2021).